ENSG00000252204
Gene: Small nucleolar RNA gene on chromosome 12 (31,811,088 to 31,811,190, forward strand). Ensembl gene ENSG00000252204.
Homologues: Paralogues in human: SNORA25B (81% identical), SNORA25 (77% identical).